MIR548H4 (microRNA 548h-4)
Synonyms: hsa-mir-548h-4; MIR548H-4; MIRN548H4
Gene: MicroRNA gene on chromosome 8 (27,048,853 to 27,048,963, reverse strand). Ensembl gene ENSG00000221616.
Gene Ontology:
Biological process: miRNA-mediated post-transcriptional gene silencing
Cellular component: RISC complex